IL6 (interleukin 6)
Diseases named in the same sentence as IL6 in open-access papers (continued):
Sharing a sentence is not in itself a finding about the gene and the disease.
lung carcinoma (continued). "The lung cancer cells (H596), exhibited no significant reduction in survival when treated with Erbitux, mAb IL6 or mAb IGF1R in monoculture." (PMID 26053043, 2015). "Despite the effects of IL-6 in ATM phosphorylation and in tumor invasion were documented respectively, the exact role of ATM phosphorylation in IL-6 increasing lung cancer metastasis is still unknown." (PMID 26528698, 2015). "Our previous studies show that the phosphorylation of ataxia-telangiectasia mutated (ATM) induced by interleukin 6 (IL-6) treatment contributes to multidrug resistance formation in lung cancer cells, but the exact role of ATM activation in IL-6 increased metastasis is still elusive." (PMID 26528698, 2015). "However, altered cytotoxic activity in AMs and tumour-associated macrophages (TAMs) has been shown to be mediated via decreased secretion of cytokines (IL-1, IL-6, and TNF-α) in patients with lung cancer." (PMID 26316944, 2014). "The E6 antigens of HPV 16 up-regulate interleukin-6 (IL-6) and anti-apoptotic Mcl-1 which, subsequently, may promote the tumor progression of HPV-infected lung cancer." (PMID 23349885, 2013). "Interestingly, receptor expression for IL-6 increased with time, while receptor expression for TNF-α and IL-1β decreased with time, in the case of lung cancer cells interacting with astrocytes." (PMID 23271367, 2012). "IL-6 has been demonstrated as a potent activator of the JAK/STAT3 pathway, and has been shown to act in an autocrine manner to induce STAT3 to contribute to the pathogenesis of lung cancer." (PMID 18939993, 2008). "IL-6 was detectable in 29 patients with lung cancer (39%), but was not detectable in any of the patients with benign lung diseases." (PMID 7734307, 1995). "However, the role of the immune system, particularly the involvement of the IL-6 promoter in radon exposure, may be considered as a future perspective and could potentially lead to the development of a specific AOP on lung cancer." (PMID 40823246, 2025). "Additionally, IL‐6 and IL‐8 promote angiogenesis in NSCLC by inducing VEGF expression, while long‐term exposure to IL‐1β induces a memory‐like epithelial–mesenchymal transition (EMT) phenotype in lung cancer tissues." (PMID 41223031, 2025). "According to the research in lung cancer done by Yi-Chang Wang and colleagues, enhanced histone-3 acetylation and decreased levels of DNMT1 and IκB is mediated by USP24 via the stabilization of p300 and β-TrCP, thereby leading to elevated IL-6 transcription in M2 macrophages." (PMID 40380196, 2025). "Besides, there are several ongoing phase 1/2 clinical trials aiming to investigate the clinical benefit of including blockade of IL-6, IL-8 or TGF-β in the treatment of patients with advanced lung cancer (IL-6: NCT05704634; IL-8: NCT04123379, NCT04572451; TGF-β: NCT03732274, NCT05537051)." (PMID 40746594, 2025). "Therefore, tocilizumab, an anti-IL-6 inhibitor, is considered one of the first drugs that can be used if systemic csDMARDs are not efficient in RA patients with lung cancer." (PMID 40282506, 2025). "We performed RNAseq analysis on A549 lung cancer cells and 122L and 153L (HMEC cultures derived from post-menopausal women), and 240L (HMEC cells derived from an 18-year-old woman) that had been treated with EGF (A549 only), TGF-β1 (HMEC only), or IL-6 (both A549 and HMEC) for six hours." (PMID 41497628, 2025). "Therefore, we concluded that IL-6 might serve as a key downstream molecule of AQP3, exerting regulatory effects on the progression and glucose metabolism of lung cancer cells." (PMID 39060229, 2024).
lung carcinoma (continued). "We examined eight key cytokines (Interleukin-1, IL-6, IL-8, IL-10, IL-12p70, monocyte chemotactic protein-1 (MCP-1), interferon-gamma (IFN-γ), and tumor necrosis factor-alpha (TNF-α)) in the plasma of 104 lung cancer patients and 48 cancer-free individuals using the FirePlex Immunoassay." (PMID 38276239, 2024). "Evidence suggests that cytokines such as interleukin-1β (IL-1β), IL-6, interleukin-7 (IL-7), interleukin-8 (IL-8), interleukin-11 (IL-11), tumor necrosis factor-alpha (TNF-α), TGF-β, and C-C motif chemokine ligand 12 (CCL12) play significant roles in the bone metastasis of lung cancer." (PMID 38571500, 2024). "IL-1β and IL-6 can induce EMT in breast cancer cells via the STAT3 pathway and promote angiogenesis, which suggests that BMAs may similarly exacerbate bone destruction in lung cancer bone metastasis." (PMID 38571500, 2024). "However in our series, IL-6 was elevated in both MM and lung cancer pleural effusions, and the IL-6 levels were not statistically different between the two diseases." (PMID 38689325, 2024). "disclosed that in lung cancer, ERO1L promotes IL6R secretion to activate the NF-κB pathway, leading to an upregulation of MUC16 gene expression, and the C-terminal of MUC16 further fosters the EMT phenotype and IL6 release, creating a positive feedback loop that exacerbates lung cancer progression." (PMID 38361923, 2024). "Lung cancer CAFs exert their immunosuppressive effects by secreting chemokines, including CCL2, chemokine (C-C motif) ligand 7 (CCL7), chemokine (C-X-C motif) ligand 1, 5, and 8 (CXCL1, CXCL5, CXCL8), and IL-6, which promote the differentiation of CD14+ monocytes into immunosuppressive MDSCs." (PMID 39834587, 2024). "Importantly, IL-6 expression is elevated in IMs from non-involved tumor-adjacent lung tissue compared to distal lung tissue in lung cancer patients, highlight the clinical relevance of our discovery." (PMID 38853850, 2024). "Additionally, conditioned media from MUFA-treated lung cancer cells had little apparent effect on the release of IL-10, M-CSF, and IL-6 from monocytes, which suggest that MUFA does not lead to a complete shift in the cytokine profile." (PMID 39100092, 2024). "Hsp70 in the exosomes of A549 lung cancer cells could bind to the TLR2 receptor and activate the NF-κB pathway, resulting in an increased secretion of inflammatory factors, including macrophage chemotactic protein-1, IL-6 and IL-8, and skeletal muscle atrophy." (PMID 38689293, 2024). "Moreover, analysis of lung tissues from patients diagnosed with lung cancer (Stages IAI-IIB) revealed significantly elevated expression levels of IL-6 within IMs located in adjacent lung tissue to tumour tissue compared to IMs in distant areas of the lung within the same patients." (PMID 38853850, 2024). "While IL-6 seems to play a role in lung cancer development in both never-smokers and ever-smokers, the possibility that IL-1β and IFN-γ may play roles in the mechanism of lung cancer development in never-smokers cannot be ruled out." (PMID 38067398, 2023). "The findings of this study, as reported in previous studies, indicate that serum IL-6 may be a potential universal biomarker for lung cancer, regardless of the histological type." (PMID 38067398, 2023). "Moreover, stimulation with TLR4 and TLR3 can induce the production of IL-6, CCL2/MCP-1, CCL20/MIP-3α, VEGFA (vascular endothelial growth factor A), and MMP2 known to play pivotal roles in the migration and invasion of lung cancer cells through induction of autophagy." (PMID 37443143, 2023). "Importantly, we found that FFAR2KO A549 and FFAR2KO H1299 lung cancer cells exhibited the enhancement of cell migration, invasion, and colony formation induced by TLR2 and TLR3, along with increases in the production of CCL2, IL-6, and MMP2 cytokines." (PMID 37287005, 2023).
lung carcinoma (continued). "The results demonstrated that serum and bronchoalveolar lavage fluid IL-6 and serum IL-8 were higher in lung cancer patients compared to non-cancer controls, suggesting that lung cancer itself upregulates the production of IL-6 and IL-8 and that the action of RT further increases BALF IL-6." (PMID 37373957, 2023). "Our research showed that CPFE with lung cancer was more common in elderly men and smokers, mainly in heavy smokers, with a more severe systemic inflammatory response represented by significantly elevated CRP, IL-6 and fibrinogen, which is in line with the results of previous studies." (PMID 36769748, 2023). "Ultimately, lower lymphocyte level could be used as an ancillary marker for diagnosis and severity in lung cancer patients, especially in centers where more expensive tests such as d-dimer, interleukin-6, and ferritin are not feasible for routine practice." (PMID 36102415, 2022). "For example, alterations of the lung and gut microbiome were associated with increased levels of several inflammatory serum cytokines, including IL-6 and TNF-α, in preclinical models of lung cancer, which could in part be remedied by the administration of probiotics." (PMID 36387148, 2022). "The analysis also reported that baseline concentrations of CRP (6.0 mg/L vs. 4.2 mg/L; p < 0.0001) and IL-6 (3.2 vs. 2.6 ng/L; p < 0.0001) were significantly higher among participants subsequently diagnosed with lung cancer than among those not diagnosed with cancer." (PMID 35872912, 2022). "Similarly, heterogeneous expression profiling of IL-6 was obtained analyzing the epithelial-derived tumors, of which cervical and pancreatic cancers showed the highest IL6 expression levels while breast and lung cancers showed the lowest ones." (PMID 34576335, 2021). "The IL-6 expression status and NK cell levels of early lung adenocarcinoma as GGO are significantly reduced, and the stimulation of IL-6 can up-regulate or activate NK cells in GGO, providing new insights into the diagnosis and pathogenesis of early lung cancer." (PMID 34568032, 2021). "Additionally, we investigated how the supernatant of lung cancer cells that do not secrete IL-6 affects the LPS-induced maturation of moDCs." (PMID 34671021, 2021). "We found two combinations that can distinguish lung cancer patients with stage IIB from those with IIA with 100% sensitivity and 100% specificity, wherein IL-6, glucose, and LDH has an AUC = 0.8333 and the combination of CEA, IL-6, SAA1, MMP-9, and lactate an AUC = 1.0000." (PMID 34439874, 2021). "Moreover, IL-6 and TNF-α could promote metastasis of lung cancer by inducing epithelial-mesenchymal transition in the animal experiment." (PMID 32595734, 2020). "Previous studies suggested that IL-37 could inhibit the activation of the NF-κB and IL-6/STAT3 signaling pathway and suppressed the occurrence of the inflammatory response in Myasthenia Gravis (MG) by affecting Tfh and B cells, and in lung cancer by affecting A549 cells." (PMID 32733162, 2020). "Therefore, in this review, we summarized the published literature from the year 2000 to the year 2019, specifically focusing on the role of IL6, TNFα, IL10, CCL2, CX3CL1, IL8 in the macrophages-tumor cells crosstalk; leading to lung cancer development and progression." (PMID 32219066, 2020). "In contrast, both pre- and clinical data have shown that K-ras mutant lung cancers demonstrate significant infiltration of multiple inflammatory cells, such as myeloid cells, CD8+ T cells, regulatory T cells (Tregs), IL-17-producing lymphocytes, and inflammatory cytokines (e.g., IL-6, IL-8, CXCL1)." (PMID 32039025, 2019). "For this reason, combinative inhibition of EGFR and IL‐6/STAT3 pathway rather than blockade of EGFR alone might therefore be more effective in the treatment of lung cancer." (PMID 31507089, 2019).
lung carcinoma (continued). "However, an increase in p300 by USP24 enhances the NF-κB level through an increased recruitment of acetyl histone H3 to the promoter of NF-κB to regulate IL-6 expression in M2 macrophages but not in lung cancer cells." (PMID 30266897, 2018). "Nevertheless, whether a link exists between the IL-6 signaling-triggered radioresistance development and the resistance induction to NK cell cytotoxicity in lung cancer is not known." (PMID 29113321, 2017). "Collectively, these findings imply that inhalation of DP2 not only reinforces invasiveness of lung carcinoma cell via activation of integrin/FAK signaling but also may promote lung carcinoma metastasis via increasing production of tumor development mediators such as uPA, MMP-2, and IL-6." (PMID 28076322, 2017). "Since our data points to a possible mechanism for how cancer cells can accelerate autophagy (i.e. IL-6 secreted from cancer cells induces autophagy via trans-signaling), we asked if an increase in IL6 mRNA in the tumor correlates with short survival of lung cancer patients." (PMID 28515477, 2017). "Moreover, IL-6 mRNA-positive cells were also found in non-cancer lung epithelial cells near a primary lung cancer lesion (arrow)." (PMID 28951614, 2017). "In order to exclude the possibility that the IL-6-expressing cells were intraepithelial lymphocytes or alveolar macrophages, we performed double staining of IL-6 mRNA and CAM5.2 in the same tissue sections and confirmed that double-positive cells definitely existed in human lung cancer tissues." (PMID 28951614, 2017). "Interestingly, human BECs collected from patients with a subsequent lung cancer diagnosis (n = 56) had significantly higher IL6 expression than those without (n = 22) (0.0029 ± 0.0034 vs. 0.0013 ± 0.0014, p = 0.027 with adjustment for the rs1800797 genotype)." (PMID 26372664, 2016). "Since our data also revealed the activation of IL-6 inflammatory feedback loop via a STAT3-NF-κB pathway, we speculated that NF-κB may down-regulate miR-124 though repressing HNF4α expression in the metastatic lung cancer cells, needing further study." (PMID 25749519, 2015). "Moreover, serum IL-6 levels were not significantly different in lung cancer patients with or without clinically demonstrated distant metastasis." (PMID 7734307, 1995). "Serum C-reactive protein levels and plasma fibrinogen levels were significantly higher and serum albumin concentration was significantly lower in lung cancer patients with detectable serum IL-6 levels than in those without detectable serum IL-6 levels and in patients with benign lung diseases." (PMID 7734307, 1995). "In addition, we have provided strong evidence that the JAK2/STAT3/C/EBPβ-induced IL-6 positive feedback pathway is important for lung cancer cell growth, migration, and invasion, which suggests that the STAT3-C/EBPβ-IL-6 signaling axis plays a crucial role in TAM-mediated lung cancer progression." (PMID 38424624, 2024). "Notably, FFAR2KO human lung cancer FFAR2KO A549 and FFAR2KO H1299 cells showed marked increases in cell migration, invasion, and colony formation in response to TLR2 or TLR3 stimulation, accompanied by elevations in NF-κB activation, cAMP levels, and the production of CCL2, IL-6, and MMP2 cytokines." (PMID 37287005, 2023). "Thus, GPX8‐mediated secretion of IL6 and CCL2 by CAF in TME may promote lung cancer metastasis." (PMID 35978854, 2022). "In conclusion, IL-6 and IL-8 could be used as promising molecular biomarkers to diagnose and predict the metastasis of lung cancer independent of pathological types, improving the specificity and sensitivity of diagnosis for lung cancer when they were combined with CEA." (PMID 35928100, 2022).
lung carcinoma (continued). "The correlation of IL-6 and MMP-9, as well as other correlations in adenocarcinoma and SqCC and differences in the biomarker concentrations among groups, allowed us to observe subtype characteristics that might possibly be used to differentiate these two most common subtypes of lung cancer." (PMID 34439874, 2021). "Thus using the well-characterized model human lung cancer model cell line (BEAS-2B), poly I:C RNA, LL37 peptide, or LL37-poly I:C complexes were loaded onto ZnO NP and delivered to BEAS-2B lung cells, and the effect on the main cancer regulating cytokine, IL-6 determined by ELISA." (PMID 31771091, 2019). "Unstimulated lung cancer peripheral leukocytes produced higher IL-6 levels than the controls while under the experimental conditions used the 2 h stimulation of PBMCs with a low dose of LPS did not induce IL-6 secretion in either the control or the patient groups." (PMID 30365491, 2018). "Interestingly, the combination of anti-IL-6 antibody and cisplatin could destroy the lung cancer organoids, while cisplatin alone could not." (PMID 28951614, 2017). "Consequently, treatments based on EGFR inhibition may not be sufficient for the effective treatment of lung-cancer patients with mutant EGFRs and it is necessary to inhibit IL-6/gp130/JAK pathway and further repress STAT3 activity in NSCLC treatment strategy." (PMID 26166037, 2015). "Thus, in agreement with IIiopoulos and colleagues, IL6 may not be a common requirement for CICs in lung cancer." (PMID 23935876, 2013). "However, since CXCR1 is highly expressed in A549 cells following exposure to DNA methytransferase inhibitors, inflammatory circuits that regulate promoter demethylation, as observed for IL6 signaling, may play an important role for controlling the IL8/CXCR1 responsiveness in lung cancers." (PMID 23935876, 2013). "Patients with baseline age ≥70 years, ECOG >0, primary lung cancer, aCharlson index >2 and/or receiving non-adjuvant ICI therapy had significantly higher pre-ICI IL-6 levels." (PMID 41019062, 2025). "Taken together, we in this study conclude that lack of SIRPα attenuated lung cancer growth in mice by reducing SHP‐1/STAT3/p38 MAPK signalling, subsequently suppressing IL‐6 expression, meanwhile improving M1 and N1 subtypes and their phagocytosis activity." (PMID 36419386, 2023). "In particular, TLR9 activation in lung cancer epithelial cells increased the release of TNF-α, but not of IL-6, through an imbalance of the ceramide/S1P rheostat in favor of S1P." (PMID 36010601, 2022). "Although, no statistically significant changes in IL-6 and TNF-α levels are found between any group of lung cancer patients (adenocarcinoma, SqCC, other NSCLC, and other neoplasms than NSCLC), there are slightly higher levels of IL-6 in SqCC patients." (PMID 34439874, 2021). "The regulatory role of ERK5 in IL-6 production is not unique to lung cancer cells, since we further confirmed ERK5-dependent IL-6 secretion in CAFs." (PMID 34671021, 2021). "Analysis of RNAseq data from lung cancer patients showed that there is a strong negative correlation between HIP-55 and interleukin-6 (IL-6) in samples from lung adenocarcinoma patients." (PMID 32134471, 2020). "To corroborate a role for IL-6 in regulating lung cancer cell proliferation, we performed the CCK-8 assay on cancer cells exposed to aADSC-CM in the presence or absence of IL-6 antibody." (PMID 31196220, 2019). "The significance of IL-17A, CRP and IL-6 suggests that not just Th-2 or Th-17 cells are important in lung cancer progression and supports our hypothesis that the inclusion of a broader cytokine panel can capture the multi-faceted role of inflammation in lung cancer." (PMID 28402963, 2017). "Importantly, IL-6 blockade alone could not kill the lung cancer stem-like cells." (PMID 28951614, 2017). "In line with this, expression of IL-6, which we found not to be regulated by TRAIL in lung cancer cells, also did not correlate with TRAIL expression in patients." (PMID 28212753, 2017).